ANK1 (ankyrin 1)
Diseases named in the same sentence as ANK1 in open-access papers (continued):
Sharing a sentence is not in itself a finding about the gene and the disease.
malaria (12 papers, 2012 to 2022). Malaria is a serious and sometimes fatal disease caused by a parasite that commonly infects a certain type of mosquito which feeds on humans. "In this study, to further understand the mechanisms underlying erythrocyte invasion by the malaria parasites Plasmodium, LC-MS was conducted to identify band 3 and ankyrin 1 (ANK1) as potential receptors for PfGAMA." (PMID 35202655, 2022). "As evidenced from this study, the protective effect of the Ank-1 gene against malaria is dependent on the nature and the location of mutations within the gene." (PMID 28751503, 2017). "Further studies should extend the understanding of the effects of various Ank-1 mutations on the development of intraerythrocytic parasites, as well as the association of HS with malaria in human populations." (PMID 28751503, 2017). "Despite the lack of direct evidence from population studies, this data further supported the protective roles of ankyrin-1 mutations in conferring malaria protection." (PMID 28751503, 2017). "On one hand, as observed with other mutations affecting red blood cell turnover, Ank1 deficits protect mice against malaria." (PMID 25268389, 2014). "Increased malaria resistance was initially observed 20 years ago in the Ank-1nb mice; however the mechanism underpinning malaria resistance in mice carrying ankyrin-1 mutations remains elusive." (PMID 22723917, 2012). "For the first time, we demonstrate that a mutation in the Ank-1 gene decreases susceptibility to malaria by reducing survival of P. chabaudi in affected RBCs." (PMID 22723917, 2012). "We conclude that increased malaria resistance due to ankyrin-1 deficiency is caused by the intraerythrocytic death of P. chabaudi parasites." (PMID 22723917, 2012). "Whether Ank-1 allelic heterogeneity in human populations has hidden an association between Ank-1 and resistance to malaria is unknown." (PMID 35646724, 2022). "Further we investigated the mechanism of malaria resistance seen in these ankyrin-1 deficient mice." (PMID 22723917, 2012). "Therefore it remains open if a deficiency of ankyrin-1 in RBCs perturbs invasion of malaria parasites." (PMID 22723917, 2012). "However, this study also describes for the first time the direct in vivo observation of different mutations in the Ank-1 gene mediating two distinct, independent mechanisms of malaria resistance, where one impairs parasite maturation and the other increases RBC clearance." (PMID 28751503, 2017). "Similarly, Ank-1 mutations described in this study, as well as other previous mouse studies, exhibit variability in malaria resistance, most likely as the result of allelic heterogeneity." (PMID 28751503, 2017). "We hypothesized that the Ank-1(MRI61689) mutation confers malaria resistance." (PMID 27848995, 2016). "Erythrocyte plasma membrane proteins were here identified as being elevated in malaria cases compared to controls and in severe malaria compared to mild malaria (GYPC) or increased in febrile convulsions compared to cerebral malaria (ANK1, MPP1)." (PMID 30442134, 2018). "Spots recognized exclusively by sera from anemic malaria patients included band 3, spectrin (both alpha and beta chains), cytoplasmic actin 1, protein 4.1, protein band 4.2, ankyrin 1, and dematin." (PMID 29884876, 2018). "This study highlights the first direct examination of allelic heterogeneity of the Ank-1 gene in the context of malaria resistance in mouse models." (PMID 28751503, 2017). "In conclusion, we have reported a novel observation where the Ank-1 gene exhibits phenotypic heterogeneity in malaria resistance mechanisms, either by impairing intraerythrocytic parasite growth or by promoting RBC clearance." (PMID 28751503, 2017). "Due to the lack of large-scale studies on the HS prevalence in malaria-endemic regions, ankyrin-1 mutations have not been associated with malaria protection." (PMID 28751503, 2017).
malaria (continued). "The heterogeneity in malaria resistance mechanisms of the Ank-1 gene as observed in this study is comparable to the two prevalent alleles of the β-globin gene, HbS and HbC, which result from amino acid substitution at position six from glutamate to either valine or lysine, respectively." (PMID 28751503, 2017). "Therefore, it is proposed that the presence of full length, or at least functional, ANK-1 protein might be an important factor in determining the detrimental effects on malaria parasites." (PMID 28751503, 2017). "Since Ank-1(MRI96570/+) and Ank-1(MRI95845/MRI95845) mice exhibited differences in malaria resistance, we hypothesized that they mediate malaria resistance through different pathways." (PMID 28751503, 2017).
Spherocytosis (7 papers, 2015 to 2023). The presence of erythrocytes that are sphere-shaped. "SPH1 (Spherocytosis, type 1), SPH2 (Spherocytosis, type 2), SPH3 (Spherocytosis, type 3), SPH4 (Spherocytosis, type 4), SPH5 (Spherocytosis, type 5) are caused by ANK1, SPTB, SPTA1, SLC4A1, and EPB42 gene mutations, respectively." (PMID 37795245, 2023).
type 2 diabetes (7 papers, 2016 to 2022). "Genome-wide association studies have identified Ankyrin-1 (ANK1) as a common type 2 diabetes (T2D) susceptibility locus." (PMID 27121283, 2016).
diabetes (6 papers, 2016 to 2023). "The ANK1 variants rs6474359 and rs4737009 were formerly considered to be linked with diabetes, when HbA1c was considered to be a primary maker for this disease." (PMID 27121283, 2016). "The locus on chromosome B1, common to both analyses, revealed coding and splice region variants in candidate genes, ANK1, EPHX2 and LOX2, implicated in diabetes mellitus and lipid dysregulation." (PMID 33154479, 2020). "Transgenic and conditional knock out animal models should be constructed to help us understand pathogeneitc of SNPs and (s)ANK1 in diabetes." (PMID 27121283, 2016). "Interestingly, the upregulation of HPT and downregulation of ANK1 were also seen in our diabetes mice, suggesting that these may be common pathways involved in vascular injury in both conditions." (PMID 36902363, 2023). "Similarly, genes ABCB11 (chromosome 2), ADCY5 (chromosome 3), CDKAL1 (chromosome 6), ANK1 (chromosome 8), GLIS3 (chromosome 9), and HKDC1 (chromosome 10) have been linked to various aspects of diabetes, including insulin release, glucose levels, β-cell function, and insulin resistance." (PMID 38274506, 2023).
Splenomegaly (6 papers, 2012 to 2026). Abnormal increased size of the spleen. "In summary, a novel de novo ANK1 c.4276C>T (p.R1426*) nonsense mutation was identified in a Chinese family affected by HS with only 10% spherical-shaped erythrocytes combined with jaundice, and splenomegaly." (PMID 29228571, 2017). "In this study, a novel de novo ANK1 c.4276C>T (p.R1426*) heterozygous nonsense mutation in the patient characterized with only 10% spherical-shaped erythrocytes in the peripheral blood, anemia, and splenomegaly, while none of his parents or his young brother carried this mutation." (PMID 29228571, 2017). "In HS and in mice lacking ANK1, the consequence of the ineffective erythropoiesis, extramedullary hematopoiesis and retention of abnormal RBC is splenomegaly and tissue iron overload leading to oxidative damage and cardiac failure." (PMID 23390527, 2013).
Parkinson disease (5 papers, 2014 to 2023). A progressive degenerative disorder of the central nervous system characterized by loss of dopamine producing neurons in the substantia nigra and the presence of Lewy bodies in the substantia nigra and locus coeruleus. "Genes showing similar co-expression patterns have been previously linked to Alzheimer’s (ANK1) and Parkinson’s disease (UBE2E2, PCMT1, HPRT1 and RIT2)." (PMID 25493648, 2014). "Furthermore, hypermethylation in ANK1 was detected also in other neurodegenerative diseases such as Huntington’s and Parkinson’s disease." (PMID 36596913, 2023).
autoimmune hemolytic anemia (4 papers, 2020 to 2023). Autoimmune hemolytic anemia (AIHA) is an autoimmune disorder in which various types of auto-antibodies are directed against red blood cells causing their survival to be shortened and resulting in hemolytic anemia. "First, there have been reported cases of autoimmune hemolytic anemia that have been associated with SARS-CoV-2 infection, a phenomenon that has been mostly attributed to the high molecular mimicry between the spike protein of SARS-CoV-2 and the protein ankyrin 1 present at RBC surface." (PMID 32825629, 2020). "Autoimmune hemolytic anemia (AIHA) was described in 14 patients with COVID-19: AIHA could be induced by a molecular mimicry between the viral spike protein and ankyrin-1, a membrane protein of erythrocytes." (PMID 35002978, 2021).
Insulin resistance (4 papers, 2020 to 2023). Increased resistance towards insulin, that is, diminished effectiveness of insulin in reducing blood glucose levels. "Among the 64 susceptible loci we examined, RASGRP1-rs7403531, ANK1-rs516946, and SEC16B-rs574367 had associations with insulin resistance." (PMID 32260174, 2020). "In recent studies, ANK1 has been reported to regulate glucose uptake in skeletal muscle, and alteration of the expression of ANK1 may induce insulin resistance." (PMID 36508323, 2023).
lung carcinoma (4 papers, 2016 to 2025). "An extensive study of miR-486-5p was recently performed in non-small cell lung cancer, showing that miR-486-5p was co-expressed with ANK1 variant 9 in lung cancer and lung epithelial cells." (PMID 35172717, 2022). "Likewise, Tessemaet al. also showed that aberrant ANK1 methylation is highly associated with patients’ smoking history in lung cancer." (PMID 31253192, 2019). "Ankyrin-1 was also induced by IR exposure in A549 lung carcinoma cells." (PMID 27054339, 2016). "Interestingly, we found that high ANK1 expression correlated with decreased survival in lung cancer, breast cancer and CLL." (PMID 27054339, 2016).
heart failure (3 papers, 2013 to 2024). Inability of the heart to pump blood at an adequate rate to meet tissue metabolic requirements. "Altered ankyrin-R (AnkR; encoded by ANK1) expression is associated with diastolic function, left ventricular remodeling, and heart failure with preserved ejection fraction (HFpEF)." (PMID 39125973, 2024). "In addition, Ank1 mutations were shown to be directly associated with dilated cardiomyopathy, cardiac hypertrophy and heart failure." (PMID 39456238, 2024). "At the whole animal level, in response to a heart failure model, Ank1-ifKO mice displayed an increase in fibrosis and T-wave inversion compared with littermate controls, while preserving cardiac ejection fraction." (PMID 39125973, 2024).
Huntington disease (3 papers, 2019 to 2023). Huntington disease (HD) is a rare neurodegenerative disorder of the central nervous system characterized by unwanted choreatic movements, behavioral and psychiatric disturbances and dementia. "Recently, research has suggested that ANK1 hypermethylation existed in the entorhinal cortex in AD, Huntington’s disease (HD) and PD, while no ANK1 DNA methylation was found in the striatum in HD or the substantia nigra in PD." (PMID 36672967, 2023).
osteosarcoma (3 papers, 2021 to 2023). A usually aggressive malignant bone-forming mesenchymal neoplasm, predominantly affecting adolescents and young adults. "In conclusion, the present study of miR-486-5p shows that the low expression observed in osteosarcoma is caused by cancer-specific methylation of the upstream promoter region of ANK1 variant 1–4." (PMID 35172717, 2022). "5-Aza-2′-deoxycytidine treatment of osteosarcoma cell lines caused induction of miR-486-5p and ANK1, indicating common epigenetic regulation in osteosarcoma cell lines." (PMID 35172717, 2022). "In osteosarcoma cell lines, ANK1 variants 1–4 were found to be moderately expressed in 8/12 lines." (PMID 35172717, 2022). "Regarding the downregulated gene ANK1, recent studies have shown that the CpG island in the ANK1 host gene promoter of mir-486 is highly methylated in osteosarcoma cell lines." (PMID 36983630, 2023). "A CpG island in the promoter of the ANK1 host gene of mir-486 was shown to be highly methylated in osteosarcoma cell lines as determined by methylation-specific PCR and direct bisulfite sequencing." (PMID 35172717, 2022). "The methylation level of ANK1 was quantified in osteosarcoma cell lines (n = 19) and normal bone samples (n = 4) using Illumina HumanMethylation27 BeadChips." (PMID 35172717, 2022). "Upon demethylation treatment, the expression levels of pri/mature miR-486 and ANK1 changed at similar levels across the osteosarcoma cell line panel, supporting a common epigenetic regulation from the ANK1 variant 1–4 gene promoter." (PMID 35172717, 2022).
pancreatic cancer (3 papers, 2016 to 2023). "The present study demonstrates that ANK1 is aberrantly expressed in pancreatic adenocarcinomas in association with promoter hypomethylation and silencing its expression in pancreatic cancer cells is associated with phenotypic changes including decreases in in vivo tumor growth." (PMID 27144336, 2016). "Next we analyzed ANK1 mRNA levels in a panel of pancreatic cancers and normal samples using quantitative RT-PCR." (PMID 27144336, 2016). "Since 5-aza-dC treatment of ANK1-silenced pancreatic cancer cell lines induces ANK1 expression, promoter methylation is an important regulator of ANK1 expression." (PMID 27144336, 2016). "Overall, our results indicate the potential value of downregulating ANK1 as a strategy for inhibiting the tumorigenicity of pancreatic cancer cells." (PMID 27144336, 2016). "Expression analysis determined ANK1 as commonly overexpressed in pancreatic cancers relative to normal pancreas." (PMID 27144336, 2016). "Since our pancreatic cancer cell lines aberrantly expressed the large isoform of ankyrin-1, for the remainder of the text we use ankyrin-1 to refer to this larger isoform." (PMID 27144336, 2016). "Using methylated CpG island amplification and promoter microarrays, we identified ANK1 as hypomethylated in pancreatic cancers." (PMID 27144336, 2016). "We also found that miR-486 is located in the coding region of ANK1 suggesting that miR-486 is co-expressed with ANK1 in pancreatic cancer cells." (PMID 27144336, 2016). "Stable knockdown of ANK1 in the pancreatic cancer cell line AsPC1 led to changes in cell morphology, and decreases in colony formation." (PMID 27144336, 2016). "We examined the expression of miR-486-3p and miR-486-5p in pancreatic cancer cell lines and its relationship to ANK-1 expression and found a tight correlation, consistent with co-expression." (PMID 27144336, 2016). "Using one such method that combines methylated CpG island amplification (MCA) and promoter microarray detection, we identified ANK1 as a hypomethylated gene in pancreatic cancers." (PMID 27144336, 2016). "Of 241 primary pancreatic cancers evaluated, 125 cases (51.9%) showed strong membrane immunolabeling for ankyrin-1 and/or diffuse labeling in the cytoplasm, whereas in the remaining 116 cases (48.1%) staining was either weakly present in the cytoplasm or completely absent." (PMID 27144336, 2016). "ANK1 was co-expressed with miR-486 in pancreatic cancer cells." (PMID 27144336, 2016). "Ankyrin-1 may be an attractive therapeutic target for pancreatic cancers." (PMID 27144336, 2016). "It is of note that other members of the ankyrin family, namely ANK1 and ANK3, have been shown to be overexpressed in multiple human cancers including breast cancer, while ANK2 overexpression has been shown in pancreatic cancer where it contributed to the malignant phenotype." (PMID 33218035, 2020). "Among patients undergoing pancreaticoduodenectomy, those with pancreatic cancers expressing ANK1 had a poorer prognosis than those without ANK1 expression." (PMID 27144336, 2016). "ANK1 expression was detected in 6 of 9 pancreatic cancer cell lines and 7 of 9 xenografts but little or no expression was detected in normal pancreatic and liver tissues or in the non-neoplastic pancreatic cell lines, HPDE and HPNE." (PMID 27144336, 2016). "The ankyrin-1 antibody detected two major bands around the expected size of 200 kDa in the control erythroleukemia cell line, K562 and in pancreatic cancer lines but not in non-neoplastic pancreatic cell lines." (PMID 27144336, 2016). "ANK1 was identified as a candidate gene undergoing promoter methylation after comparing promoter methylation profiles of the pancreatic cancer line, Panc-1 and the non-neoplastic pancreatic epithelial cell line, HPDE by using MCA in conjunction with the Agilent 44K promoter array." (PMID 27144336, 2016).
pancreatic cancer (continued). "We also examined ANK1 expression in our Serial Analysis of Gene Expression (SAGE) database and found ANK1 was expressed in 18 (75%) of 24 pancreatic cancer samples but was not expressed in microdissected normal pancreatic duct or in the non-neoplastic cell line, HPDE." (PMID 27144336, 2016).
parasitemia (3 papers, 2012 to 2017). "From those results we conclude that deficiency in ankyrin-1 results in increased death of the intraerythrocytic parasites which inversely affects the course of parasitemia resulting in resistance to malarial infection." (PMID 22723917, 2012). "Female mice, heterozygous for the Ank-1 mutation showed increased survival to infection by Plasmodium chabaudi adami DS with a concomitant 30% decrease in parasitemia compared to wild-type, isogenic mice (wt)." (PMID 22723917, 2012). "This experiment suggested that two possible mechanisms of resistance are both operating to produce the lower parasitemia and increased survival in Ank-1(MRI61689/+) mice, the reduction of parasite invasion and increased clearance of Ank-1(MRI61689/+) RBCs." (PMID 27848995, 2016). "Labeled RBCs from either wild-type, Ank-1(MRI96570/+), or Ank-1(MRI95845/MRI95845) mice were injected into infected wild-type mice of 1–10% parasitemia during late schizogony stage, and the parasitemia of each genotype was monitored over 36–40 hr to indicate relative invasion rates." (PMID 28751503, 2017). "Ank-1(MRI96570/+) and Ank-1(MRI95845/+) mice showed significant reduction in peak parasitemia of ∼15–20%, while Ank-1(MRI95845/MRI95845) mice showed ∼30% reduction in peak parasitemia compared to wild type." (PMID 28751503, 2017). "Ank-1(MRI95845/MRI95845) mice also showed a 2-d delay in parasitemia, peaking on day 12 postinfection rather than day 10 as with wild type." (PMID 28751503, 2017). "Secondly, the Ank-1(MRI61689/+) erythrocytes might be resistant to merozoite invasion, which resulted in reduced parasitemia and delayed course of infection." (PMID 27848995, 2016). "Lower parasitemia ratio (approximately 0.55) was observed from 30 minutes after injection with labelled blood, and was consistently lower in Ank-1(MRI61689/+) blood over 36 hours post injection, which indicates a lower invasion rate into the Ank-1(MRI61689/+) RBCs." (PMID 27848995, 2016). "The Ank-1(MRI96570/+) mice exhibited no significant reduction in RBC numbers, whereas Ank-1(MRI95845/MRI95845) mice were found to have a significantly shorter half-life of ∼6 d, which did not correlate with the parasitemia curve." (PMID 28751503, 2017). "The Ank-1(MRI61689/+) mice exhibited significantly lower peak parasitemia, with only approximately 13% parasitemia compared to 52% parasitemia of wild-type but no delay in the appearance of parasites was observed." (PMID 27848995, 2016). "However, the parasitemia measurements during the IVET assays were ∼2% to 16–30%, which did not correlate with the reduction of labeled Ank-1(MRI95845/MRI95845) erythrocytes." (PMID 28751503, 2017).